CCNT1 (cyclin T1)
Description:
Regulatory subunit of the cyclin-dependent kinase pair (CDK9/cyclin-T1) complex, also called positive transcription elongation factor B (P-TEFb), which facilitates the transition from abortive to productive elongation by phosphorylating the CTD (C-terminal domain) of the large subunit of RNA polymerase II (RNA Pol II). Required to activate the protein kinase activity of CDK9: acts by mediating formation of liquid-liquid phase separation (LLPS) that enhances binding of P-TEFb to the CTD of RNA Pol II. (Microbial infection) In case of HIV or SIV infections, binds to the transactivation domain of the viral nuclear transcriptional activator, Tat, thereby increasing Tat's affinity for the transactivating response RNA element (TAR RNA). Serves as an essential cofactor for Tat, by promoting RNA Pol II activation, allowing transcription of viral genes.
Synonyms: CycT1; CCNT; HIVE1
Tractability: Small molecule: a structure with a bound ligand is known; a high-quality ligand is known; it has a binding pocket of medium quality; it belongs to a druggable protein family. PROTAC: UniProt records ubiquitination sites on it; ubiquitination databases record sites on it; its protein half-life has been measured; a small molecule that binds it is known.
Target class: Other cytosolic protein
Gene: Protein-coding gene on chromosome 12 (48,688,458 to 48,716,998, reverse strand). Ensembl gene ENSG00000129315.
Subcellular location: Nucleus
Subcellular location (Human Protein Atlas): Nucleoplasm; Cytosol
Pathways (Reactome):
Disease: Formation of HIV elongation complex in the absence of HIV Tat; Formation of HIV-1 elongation complex containing HIV-1 Tat; HIV elongation arrest and recovery; Interactions of Tat with host cellular proteins; Pausing and recovery of HIV elongation; Pausing and recovery of Tat-mediated HIV elongation; Tat-mediated HIV elongation arrest and recovery; Tat-mediated elongation of the HIV-1 transcript
Gene expression (Transcription): Formation of RNA Pol II elongation complex; RNA Polymerase II Pre-transcription Events; RNA Polymerase II Transcription Elongation; RNA polymerase II transcribes snRNA genes
Signal Transduction: Estrogen-dependent gene expression; SMAD2/SMAD3:SMAD4 heterotrimer regulates transcription
Gene Ontology:
Molecular function: 7SK snRNA binding; cyclin-dependent protein serine/threonine kinase activator activity; DNA binding; DNA-binding transcription factor binding; molecular condensate scaffold activity; protein binding; RNA polymerase binding; chromatin binding; cyclin-dependent protein serine/threonine kinase regulator activity; protein kinase binding; snRNA binding; transcription cis-regulatory region binding
Biological process: host-mediated activation of viral transcription; positive regulation of transcription by RNA polymerase II; positive regulation of transcription elongation by RNA polymerase II; positive regulation of DNA-templated transcription, elongation; regulation of cyclin-dependent protein serine/threonine kinase activity; transcription by RNA polymerase II; regulation of transcription by RNA polymerase II
Cellular component: cyclin/CDK positive transcription elongation factor complex; nucleolus; nucleoplasm; nucleus; P-TEFb complex
Genetic constraint (gnomAD): Loss-of-function variants: 8 observed, 46.52 expected, observed/expected ratio (o/e) 0.17, 90% interval 0.1 to 0.31. The upper end of that interval is the gene's LOEUF score, 0.31, which puts it in group 1 of 6, group 1 being the genes least tolerant of losing a copy. Missense variants: 678 observed, 798.85 expected, observed/expected ratio (o/e) 0.85, 90% interval 0.8 to 0.9. Synonymous variants: 286 observed, 287.75 expected, observed/expected ratio (o/e) 0.99, 90% interval 0.9 to 1.1.
Homologues: Orthologues: chimpanzee CCNT1 (99% identical), macaque CCNT1 (99% identical), dog CCNT1 (94% identical), guinea pig CCNT1 (92% identical), rabbit CCNT1 (91% identical), rat Ccnt1 (91% identical), mouse Ccnt1 (90% identical), pig CCNT1 (88% identical), zebrafish ccnt1 (54% identical), Drosophila melanogaster CycT (28% identical), Caenorhabditis elegans cit-1.2 (17% identical), Caenorhabditis elegans cit-1.1 (15% identical), and 2 more. Paralogues in human: CCNT2 (46% identical), CCNK (19% identical), CCNL1 (16% identical), CCNL2 (15% identical), CCNH (10% identical), CCNQ (7% identical).